GPC3 (glypican 3)
Diseases named in the same sentence as GPC3 in open-access papers (continued):
Sharing a sentence is not in itself a finding about the gene and the disease.
liver disease (11 papers, 2010 to 2026). "The European Association for the study of liver disease published recommendation in 2012 that “immunostaining for GPC3, HSP70, and glutamine synthetase and/or gene expression profiles (GPC3, LYVE1, and survivin) is recommended to differentiate high grade dysplastic nodules from early HCC." (PMID 24369506, 2013). "A relevant biological aspect to consider is the influence of liver disease etiology on GPC-3 expression and secretion." (PMID 41511652, 2026). "Subgroup analysis of mRNA revealed that by comparing the superiority index, KIAA0101 mRNA and GPC-3 mRNA emerged as the optimal diagnostic biomarkers for distinguishing HCC from healthy individuals and liver disease patients, respectively." (PMID 39935848, 2024). "Through sensitivity and specificity analysis, it was discovered that KIAA0101 mRNA exhibits the highest sensitivity in distinguishing HCC from liver disease patients, whereas GPC-3 mRNA and GP-73 mRNA demonstrated the highest specificity." (PMID 39935848, 2024). "In a cohort of HCV-infected patients with liver disease, high levels of GPC3 transcript and protein appeared as good markers of early stages of HCC, discriminating from dysplastic nodules." (PMID 34065048, 2021). "Serum Glypican-3 (GPC3) levels in HCC patients are significantly higher than those in healthy individuals or patients with non-malignant liver diseases, making it a diagnostic marker for HCC." (PMID 41471145, 2025). "Of course, further studies are required to determine the pathogenesis, significance, and other potential diagnostic uses of GPC3 in non-neoplastic liver disease." (PMID 24498024, 2014). "During HCV-mediated liver disease and HCC, the virus, and in particular its membrane glycoprotein E2, which binds CD81, was shown to mimic GPC3 in infected hepatocytes, thereby interfering with the GPC3/CD81 binding." (PMID 34065048, 2021). "Patients with HCC have substantially elevated serum GPC3 levels compared to healthy volunteers and patients with noncancerous liver diseases." (PMID 37568696, 2023).
lung adenocarcinoma (11 papers, 2012 to 2025). A carcinoma that arises from the lung and is characterized by the presence of malignant glandular epithelial cells. "The cytokeratin 5/6 was suggested as the best marker for differentiating lung squamous carcinoma and lung adenocarcinoma, although GPC3 and others were also differentially expressed compared with controls." (PMID 28510121, 2017). "Oligonucleotide microarray analysis demonstrated that GPC3 is over-expressed in tissues harvested from smokers with lung adenocarcinoma." (PMID 28510121, 2017). "First, we demonstrated by immunohistochemistry (IHC) that GPC3 was expressed in 66.3% of LSCC samples and in 3.3% of lung adenocarcinoma (LAD) samples but not in normal lung tissues." (PMID 26684028, 2016).
mesothelioma (11 papers, 2012 to 2025). A usually malignant and aggressive neoplasm of the mesothelium which is often associated with exposure to asbestos. "Conversely, GPC3 expression was diminished in lung adenocarcinoma, mesothelioma, clear cell renal carcinoma, and ovarian and gastric cancers." (PMID 36676710, 2022).
esophageal squamous cell carcinoma (10 papers, 2017 to 2025). Esophageal squamous cell carcinoma (ESCC) is a type of esophageal carcinoma (EC) that can affect any part of the esophagus, but is usually located in the upper or middle third. "TAAs comprise a range of self-derived proteins, such as a-fetoprotein (AFP), glypican-3 (GPC-3), New York esophageal squamous cell carcinoma (NY-ESO-1) or the melanoma-associated gene-A (MAGE-A) that can become immunogenic in HCC either by mutation or aberrant expression." (PMID 31497249, 2019). "Indeed, cellular response has been detected against alpha-fetoprotein (AFP), glypican-3 (GPC-3), melanoma-associated genes (MAGE)-1, 3, and 10, synovial sarcoma X (SSX)-2, and New York-esophageal squamous cell carcinoma-1 (NY-ESO-1) in blood, as well as in the tumors of HCC patients." (PMID 35216137, 2022). "In addition, 25% of esophageal adenocarcinomas (2/8) and 26.5% of esophageal squamous cell carcinoma (SCC; (5/19) showed increased expression of GPC3 in contrast to previous studies that reported lower frequencies of positive staining for GPC3 in esophageal SCC." (PMID 31100935, 2019). "Currently, with respect to HCC, a number of TAAs have been identified: α-fetoprotein (AFP), New York esophageal squamous cell carcinoma-1 (NY-ESO-1), melanoma antigen gene (MAGE) family, glypican-3 (GPC3), and so on." (PMID 30116759, 2018).
glioblastoma (10 papers, 2015 to 2025). The most malignant astrocytic tumor (WHO grade IV). "This proteoglycan was highly prevalent in glioblastoma cells, being primarily localized in the cellular membrane and extracellular vesicles, occasionally with glypican-3." (PMID 32180897, 2020). "Recent studies have also showed a down-modulation of Glypican-3 and an up-regulation of Glypican-1 gene expression in glioblastoma." (PMID 26517809, 2015). "Furthermore, glioblastoma remodels human neural circuits by secreting synaptogenic factors (such as thrombospondin-1 and glypican-3), which promote functional tumor and neuronal connectivity while reducing patient survival." (PMID 39268034, 2024).
embryonal tumors (8 papers, 2002 to 2025). "In conclusion in this preliminary study, we have identified somatic mutations in the GPC3 gene in two of 41 cases of WT, providing evidence of a link between developmental genes and embryonal tumours." (PMID 12085187, 2002). "Nevertheless, across multiple studies, the extent of immunohistochemical (IHC) expression of GPC3 is relatively consistent for any given histology of embryonal tumor, each of which is to be reviewed in detail below." (PMID 30873384, 2019). "This mini review evaluates the biological role of GPC3, synthesizes the published expression data in pediatric solid embryonal tumors, and describes the current immunotherapeutic approaches to target GPC3." (PMID 30873384, 2019). "Owing to the potential involvement of GPC3 expression in the aetiology of embryonal tumours, we tested the methylation status of the GPC3 promoter in DNA samples derived from both normal and embryonal tumour cells." (PMID 15083193, 2004). "Thus the apparent deregulation of the GPC3 mRNA expression reported in embryonal tumours is likely to involve other regulatory signals." (PMID 15083193, 2004). "Components of embryonic cancer included: OCT3/4(+), PLAP (weak +), CD30 (+), GPC3(weak +); Yolk sac tumor components included: OCT3/4(-), GPC-3(+)." (PMID 40308496, 2025). "GPC3 and Ki67 gene expression patterns correlate with EZH2 expression with higher expression in embryonal tumors." (PMID 40766612, 2025). "GPC3 drives cell growth and inhibits differentiation via alterations in Wnt/β-catenin, Hedgehog, and FGF signaling which are often aberrantly expressed in pediatric embryonal tumors." (PMID 30873384, 2019).
gastric adenocarcinoma (8 papers, 2016 to 2025). "In gastrointestinal cancers, diagnostic biomarkers such as SALL4 and Glypican 3 are used to identify "gastric adenocarcinoma or CRAC with enteroblastic differentiation (GAED or CRAED)," but JIAED has not been reported previously." (PMID 40403397, 2025). "Both the serum AFP level and immunohistochemical expression of AFP/GPC3/SALL4 can be used to indicate a poor prognosis for gastric adenocarcinoma." (PMID 34706681, 2021). "Several studies have reported, that GPC3 is an oncofetal protein, which is associated with the alpha-fetoprotein-producing (AFP) hepatoid phenotype of gastric adenocarcinoma and gastric adenocarcinoma of enteroblastic differentiation." (PMID 31100935, 2019). "Histopathological examination revealed that the type 3 lesion contained cells with pale sporangia, and immunohistochemistry was positive for SALL4, α-fetoprotein, and Glypican-3, leading to a diagnosis of gastric adenocarcinoma with enteroblastic differentiation (GACED)." (PMID 41041100, 2025). "Intriguingly, the common gastric adenocarcinomas express the oncofetal proteins GPC3 and AFP." (PMID 31100935, 2019). "In this study, we collected gastric adenocarcinoma cases with definite sAFP levels and then analyzed their clinicopathological characteristics and immunohistochemical results of AFP, GPC3, and SALL4." (PMID 34706681, 2021).
Hepatitis (8 papers, 2014 to 2023). Inflammation of the liver. "However, when hepatitis occurs, the expression level of GPC3 in liver cells also increased." (PMID 32462022, 2020). "The mRNA expression of GPC-3 was related to OS in pathological stage (III), grade (II), vascular invasion (micro), sorafenib treatment, alcohol consumption, and hepatitis." (PMID 33902495, 2021). "Furthermore, serum GPC3 level is higher in HCC patients than that in healthy individuals and hepatitis patients." (PMID 25378766, 2014). "Currently, many studies have found that GPC3 expression is increased in HCC tissues, even though its expression is absent in the hepatocytes of healthy individuals and hepatitis patients." (PMID 25378766, 2014).
liver fibrosis (8 papers, 2014 to 2025). "In biliary atresia liver, there was a favorable correlation between the expression of glypican-3 and the grade of hepatic fibrosis in biliary atresia." (PMID 40564035, 2025). "GPC3 was negatively correlated with all liver fibrosis and ductular reaction markers and subsequently selected as the hub gene for this subtype." (PMID 36816373, 2023). "The validation cohort showed GPC3 was negatively correlated with all liver fibrosis markers ACTA2, COL1A1, COL1A2, COL3A1 and ductular reaction markers KRT7 and KRT19, while SDC4 was positively correlated with ductular reaction index KRT19." (PMID 36816373, 2023). "Hepatic fibrosis (hazard ratio [HR], 5.706; 95% confidence interval [CI], 1.700–19.153; p = 0.005) and postoperative plasma GPC3 positivity (HR, 3.575; 95% CI, 1.239–10.314; p = 0.018) were significantly correlated with the risk of recurrence." (PMID 28035063, 2017). "In BA's liver tissues, we found that GPC3 was mostly expressed in hepatocytes, indicating GPC3 might stabilize the function of hepatocytes rather then participate in the liver fibrosis and ductular reaction directly." (PMID 36816373, 2023). "The decreased expression for GPC3 simultaneously with the decreased PCNA in the MSCs-transplanted rat livers proved the potential of MSCs in preventing progression of preneoplastic transformation initially triggered by CCl4 liver fibrosis." (PMID 31781620, 2019). "Accordingly, we found increased mRNA levels of liver fibrosis (Col1a1, Col3a1, α-Sma, Tgf-β1) and HCC markers (Afp and Gpc3) at 3 months and 6 months, suggesting the successfully constructed DEN/CCl4-induced liver fibrosis and primary HCC model." (PMID 40180937, 2025). "Several combinations have been proposed, such as the SAFE biopsy algorithm for the non-invasive assessment of liver fibrosis, which consists of APRI and a commercialized method (Fibrotest-Fibrosure) or the combination of GP73, glypican-3, and AFP for the diagnosis of HCC." (PMID 34298722, 2021).
metastatic carcinoma (7 papers, 2013 to 2024). A carcinoma which has spread from the original site of growth to another anatomic site. "They all recommend to use of Arg-1 with HepPar-1 and glypican-3 as a panel in distinguishing HCC from metastatic carcinoma." (PMID 37874737, 2023). "Typically, these are studies looking at the value of GPC3 as a site-specific marker to determine if a tumor is of hepatocellular origin or if it could represent a metastatic carcinoma from another site." (PMID 39598037, 2024). "Glypican-3 (GPC3) is an oncofetal heparan sulfate proteoglycan that is currently used as a diagnostic biomarker for distinguishing HCC from normal liver tissue, benign hepatic tumors, and other types of metastatic carcinomas." (PMID 31141571, 2019).
osteosarcoma (7 papers, 2021 to 2025). A usually aggressive malignant bone-forming mesenchymal neoplasm, predominantly affecting adolescents and young adults. "Osteosarcoma cells overexpressing mutated GPC3 exhibit multidrug resistance, indicating the need for novel agents with new mechanisms of action." (PMID 40138604, 2025). "Through the Transwell experiment, the proliferative ability of GPC3 on osteosarcoma cells was verified, revealing that after knocking down GPC3, the migration and invasion abilities of osteosarcoma cells significantly declined." (PMID 40433364, 2025). "In osteosarcoma, GPC3 has been shown to colocalize with active β-catenin on the cell membrane, and treatment with a specific anti-GPC3 antibody led to less β-catenin localization." (PMID 40650246, 2025). "Besides IHH and GLI1, GPC3, which is downregulated in our poor prognosis osteosarcoma sub-group, has been shown to inhibit Hedgehog signaling in mouse development and in vitro in NIH 3T3 cells." (PMID 38538763, 2024). "Six of these genes are increased (MYOM2, VEGFA, MUC1, IHH, GLI1 and GRIA1) and seven are decreased (VCAM1, EGFR, GPC3, IGF2, GNG12, GNGT1 and C3) in localized patients with poor prognosis that either relapse or die due to osteosarcoma." (PMID 38538763, 2024). "Most gene targets commonly investigated in ACT of other solid tumors except osteosarcoma, such as CEACAM1, PSCA, MSLN, IL13RA2, and GPC3, showed low or nonspecific expression in osteosarcoma compared with adjacent normal tissues." (PMID 37457661, 2023).
overgrowth syndrome (7 papers, 2007 to 2025). A group of syndromes caused by genetic birth defects that may lead to the development of malignancies. "GPC-3 deficiency in mice leads to an overgrowth syndrome, which aligns with its reported function to inhibit of cell proliferation." (PMID 31391540, 2019). "GPC3 is believed to play a crucial regulatory role in cellular proliferation in embryonic mesodermal tissues since deletion of the GPC3 gene leads to the development of gigantism/overgrowth syndrome known as Simpson–Golabi–Behmel syndrome (SGBS)." (PMID 31510063, 2019).
metastatic tumors (6 papers, 2011 to 2025). "While classical markers, such as HepPar1, Arg-1, and GPC3, remain foundational for distinguishing HCC from benign lesions and metastatic tumors, their limitations in specificity and sensitivity underscore the need for combinatorial approaches." (PMID 40941632, 2025). "GPC3 appeared underexpressed in 100 % of non-metastatic CRCs analyzed (p = 0.018), with the average decrease being approximately 14 fold, while only 50 % of metastatic tumors showed alteration in levels of this glypican." (PMID 26482785, 2015). "The qRT-PCR results were unable to detect significant diferences in the levels of transcripts except for Glypican-3 (GPC3), in which 85% of non-metastatic (p = 0.003) and all metastatic tumors (p = 0.005) evidenced a strong (approximately 10 fold and 12 fold respectively) sub-expression." (PMID 23327652, 2013). "Immunohistochemical examination demonstrated that the tumor cells were positive for glypican-3 (GPC3), alpha-fetoprotein (AFP), hepatocyte paraffin-1 (Hep Par 1), cytokeratin 18 (CK 18), and hepatocyte antigen, which confirmed that the seminal vesicle tumor was a metastatic tumor of HCC." (PMID 21443783, 2011).
pediatric cancers (6 papers, 2019 to 2025). "ROBO1 and GPC3 are also expressed on the cell membrane in some types of cancer, and the five antigens also cover various pediatric cancers." (PMID 40076777, 2025). "Pediatric malignancies derived from tissues that express GPC3 during development, such as the liver or kidney, frequently demonstrate upregulation of GPC3 which is likely important to both malignant transformation and tumorigenesis in these childhood cancers." (PMID 30873384, 2019). "In summary, this article reviews the current evidence for targeting childhood cancers with GPC3-directed immunotherapies." (PMID 30873384, 2019). "Our CAR-T therapy targeting five common membrane protein cancer antigens—EphB4, CLDN1, LAT1, ROBO1, and GPC3—may be effective against many solid tumors, including childhood cancers." (PMID 40076777, 2025). "It is not fully understood how these childhood cancers are able to re-induce GPC3 expression." (PMID 30873384, 2019).
renal carcinoma (6 papers, 2014 to 2024). A carcinoma arising from the epithelium of the renal parenchyma or the renal pelvis. "We constructed a GPC3 expression vector and transfected the renal carcinoma cell lines, 786-O and ACHN." (PMID 25168166, 2014). "GPC3 blocks the cell cycle in renal cancer cells 786-O and ACHN at G1 phase." (PMID 33302876, 2020). "To assess the potential role of GPC3 in this type of cancer, we performed assays in the 786-O and ACHN renal carcinoma cell lines." (PMID 25168166, 2014). "Although it was informed that the overexpression of GPC3 did not affect the apoptosis of renal carcinoma cells, our studies showed that MCF-7-sh GPC3 cells were less susceptible to death, while MDA-MB231-GPC3 died more after starvation." (PMID 27507057, 2016). "Our results suggest that cells overexpressing GPC3 in renal cell carcinoma do not induce apoptosis; therefore, we hypothesized that the inhibition of cell proliferation in renal carcinoma cells might occur due to cell cycle arrest." (PMID 25168166, 2014).
rhabdomyosarcoma (6 papers, 2010 to 2022). A rare aggressive malignant mesenchymal neoplasm arising from skeletal muscle. "A significant minority of rhabdomyosarcomas express GPC3, specifically 107/351 (31%) cases were positive in 3 different studies including both embryonal and alveolar subtypes." (PMID 30873384, 2019). "Of all the glypicans, GPC3 exhibits the greatest homology with glypican 5 (GPC5), which is located on 13q32, a region of frequent genomic amplification in rhabdomyosarcomas and specifically associated with the PAX7-FOXO1 fusion." (PMID 30873384, 2019). "GPC3 expression is reported in rhabdomyosarcoma and undifferentiated soft tissue sarcomas." (PMID 34572932, 2021). "Nevertheless, other proteoglycans are also involved in rhabdomyosarcoma, such as chondroitin sulfate proteoglycan 4 (CSPG4) and glypican-3 (GPC3)." (PMID 35128576, 2022). "Expression of GPC3 has also been demonstrated in rhabdomyosarcoma, but not in adult soft tissue sarcomas." (PMID 35128576, 2022).
acute respiratory distress syndrome (5 papers, 2017 to 2024). Progressive and life-threatening pulmonary distress in the absence of an underlying pulmonary condition, usually following major trauma or surgery. "Furthermore, GPC3 has been illustrated to be a potential biomarker candidate for HCC, acute respiratory distress syndrome and severe pneumonia." (PMID 31160489, 2019).
clear cell carcinoma (5 papers, 2014 to 2025). "Overexpression of glypican-3 may be related to low-level proliferation of tumor cells and is associated with resistance to chemotherapy and poor prognosis of clear cell carcinoma." (PMID 29963273, 2018). "A study in Japan showed that GPC3 expression was observed in 44% of clear cell adenocarcinomas, whereas it was rarely observed in other histological subtypes." (PMID 38824600, 2024). "SALL4 is a highly sensitive and specific marker for OGCT and is particularly useful in differentiating yolk sac tumors from clear cell carcinoma, where other markers, such as AFP or glypican-3, show lower sensitivity and specificity." (PMID 41373846, 2025). "GPC3 is especially valuable for distinguishing YST from clear cell carcinoma and other germ cell tumors, as it is negative in teratomas, embryonal carcinomas, and germinomas." (PMID 41373846, 2025).